FBLN1 (fibulin 1)
Diseases named in the same sentence as FBLN1 in open-access papers (continued):
Sharing a sentence is not in itself a finding about the gene and the disease.
asthma (8 papers, 2010 to 2024). "In respiratory diseases, FBLN1 is implicated in fibrosis and inflammation, key components of conditions like asthma and chronic obstructive pulmonary disease (COPD)." (PMID 39671383, 2024). "In asthma the presence of fibulin-1 in the ECM deposited by ASM cells promotes cell proliferation, particularly in ASM from asthmatic donors." (PMID 34877523, 2021). "FBLN1 levels are increased in serum and bronchoalveolar lavage fluid of asthma patients and in the plasma and lung tissue of IPF patients." (PMID 33826640, 2021). "The increased FBLN-1 resulted in exaggerated proliferation and wound repair in asthma derived ASM cells which was reduced when only the FBLN-1C isoform was downregulated." (PMID 20967215, 2010). "In the present study, we demonstrated for the first time that the expression of FBLN-1 is increased in asthma." (PMID 20967215, 2010). "We demonstrated that TGFβ not only increased FBLN-1 in asthma derived ASM cells, but also enhanced its deposition in the asthmatic ECM." (PMID 20967215, 2010). "We have previously found elevated FBLN-1 in the serum and lung washing fluid (bronchoalveolar lavage) of people with asthma, and furthermore shown FBLN-1 to regulate airway smooth muscle (ASM) cell proliferation, therefore highlighting the potential role of FBLN-1 in airway wall remodelling." (PMID 23762390, 2013). "This suggests that FBLN-1 may play a pivotal role in the processes that drive airway wall lesions in asthma that lead to enhanced airways reactivity." (PMID 20967215, 2010). "In addition fibulin-1 was increased in asthma derived airway smooth muscle cells and fibulin-1C contributed to the enhanced proliferation and wound repair in these cells." (PMID 20967215, 2010). "However, the function of FBLN-1 in the lungs and its role in asthma is unknown." (PMID 20967215, 2010). "FBLN-1 levels were greater in volunteers with asthma compared with those without asthma and these levels were not altered by in vivo corticosteroid treatment." (PMID 20967215, 2010). "The objective of this study was to study the expression of fibulin-1 in volunteers with and without asthma, and to examine its function in vitro." (PMID 20967215, 2010). "If, as our results in the present study suggest, FBLN-1 is implicated in airway remodeling, then the lack of effect of corticosteroids on levels of FBLN-1 in-vivo highlights the need for treatments that target the structural changes which contribute to airway remodeling in asthma." (PMID 20967215, 2010). "The current study demonstrates that FBLN-1 is differentially expressed in ASM from volunteers with and without asthma." (PMID 20967215, 2010).
lung carcinoma (8 papers, 2014 to 2025). "For example, recent findings demonstrate that secretory proteins such as Cathepsin F and Fibulin-1 serve as novel circulating diagnostic biomarkers, enabling early detection and clinical monitoring of brain metastases in lung cancer patients." (PMID 40225580, 2025). "Among them, GRHL2 was reported to be associated with EMT status in lung cancer, and FBLN1 was once reported as novel diagnostic biomarkers in both tissue and serum of lung cancer patients." (PMID 41214581, 2025). "Emerging data have indicated that the fibulin (FBLN) family comprising seven members (fibulin-1–7) of widely expressed ECM proteins is associated with lung cancer invasion and metastasis." (PMID 34976811, 2021). "This study in identifying a role for matrix FBLN1 in regulating EGFR activation in NSCLC Calu-1 cells further adds to our understanding of this regulatory crosstalk in lung cancers." (PMID 32719793, 2020). "Our results show that FBLN1 suppresses EGFR activation, and that loss of FBLN1C/FBLN1D (as seen in lung cancers) can promote EGFR dependent cellular function." (PMID 32719793, 2020). "To test the expression of FBLN1 in lung cancers we first evaluated the TCGA lung cancer dataset and detected ∼ 2.41 fold decrease in FBLN1 transcript levels in lung cancer samples relative to normal lung." (PMID 32719793, 2020). "This could further drive the impact FBLN1 downregulation has on EGFR dependent lung cancer cells (NSCLC)." (PMID 32719793, 2020). "With the known role EGFR activation and localization to the mitochondria has in lung cancer cells, evaluating the impact matrix Fibulin-1 could have in mediating mitochondrial function would be of much interest." (PMID 32719793, 2020). "FBLN1 is one of the regulators of TGFβ signaling, is downregulated in lung cancer, has been suggested to be a tumor suppressor by inducing apoptosis and at the same time is antiapoptotic through Notch signaling, and its mechanism of action remains still unknown." (PMID 34572749, 2021). "For example, FBLN1 and FOXO4, well-known lung cancer suppressor genes, showed significantly lower expression in the A549 cells than in the BEAS-2B cells (log2 fold change < −1 and adjusted P value < 0.01)." (PMID 36702236, 2023). "We also sought to establish a prediction model for early detection of BM in patients with lung cancer based on the CTSF and FBLN1." (PMID 35217799, 2022). "ROC curve analysis was used to evaluate the performance of CTSF and FBLN1 as serum biomarkers for diagnosing NSCLC BM, compared with the classical serum biomarkers for lung cancer (CEA, CA125, SCC, CYFRA211)." (PMID 35217799, 2022). "Although a large number of matrix proteins are altered in lung cancers, the functional role of some of the major lung ECM proteins like Fibulin-1, Elastin, Nephronectin, Agrin, Laminin remain poorly documented." (PMID 32719793, 2020). "Both FBLN1, FBLN3 are highly expressed in normal adult lung and downregulated in lung cancer cells (NSCLC)." (PMID 32719793, 2020). "This study reveals the role FBLN1 isoforms FBLN1C and FBLN1D as part of the CDM have in regulating EGFR activation and function in lung cancer cells." (PMID 32719793, 2020). "To test the possible role FBLN1 isoforms could have in regulating EGFR signaling and function in lung cancer, we performed siRNA mediated knockdown of FBLN1C and FBLN1D in NSCLC Calu-1 cells." (PMID 32719793, 2020).
pulmonary fibrosis (8 papers, 2015 to 2024). Chronic progressive interstitial lung disorder characterized by the replacement of the lung tissue by connective tissue, leading to progressive dyspnea, respiratory failure, or right heart failure. "We found significant increases in lung mRNA for Fibulin 1 and Fibulin 2, which have been implicated in pulmonary fibrosis." (PMID 37761959, 2023). "The observed upregulation of Fibulin 1 in our wound healing model corresponds to a study on patients with pulmonary fibrosis." (PMID 38247855, 2024). "Similarly, Fbln1 encodes an ECM glycoprotein which is upregulated in the setting of pathogenic fibrosis, such as in diseases like idiopathic pulmonary fibrosis." (PMID 39056733, 2024). "FBLN1 has been involved in airway remodeling in chronic asthma and pulmonary fibrosis." (PMID 34977033, 2021). "Fibulin-1 is an extracellular matrix (ECM) protein, levels of which are elevated in serum and lung tissue from patients with idiopathic pulmonary fibrosis compared to healthy volunteers." (PMID 25834989, 2015). "In comparison to the neutrophilic cases, the IPA analysis of the proteomic datasets derived from horses with metachromatic inflammation revealed enrichment in pathways related to hypersensitivity reaction (CD44, ICAM1, SOD1, PSAP, CDH1) and lung fibrosis (AGER, TGFBR2, FBLN1, S100A9)." (PMID 39594673, 2024).
type 2 diabetes (8 papers, 2012 to 2022). "In conclusion, plasma fibulin-1 was independently associated with increased PWV in a sample of well-regulated patients with recently diagnosed type 2 diabetes and gender- and age-matched controls." (PMID 23866070, 2013). "Further studies are needed to determine the exact role of fibulin-1 in arterial stiffness and cardiovascular risk in patients with type 2 diabetes." (PMID 23866070, 2013). "The elastin-associated extracellular matrix protein, fibulin-1, was recently found in higher concentrations in the arterial wall and in plasma in patients with long duration type 2 diabetes." (PMID 23866070, 2013). "Thus, in this study we sought to i) compare the plasma-fibulin-1 levels in patients with recently diagnosed type 2 diabetes with a gender- and age-matched control group and ii) to study the association between plasma fibulin-1 levels and PWV." (PMID 23866070, 2013). "FBLN1 is abundant in the plasma and arterial walls of patients with type 2 diabetes and can be used as a predictor of cardiovascular mortality in patients with type 2 diabetes." (PMID 35745003, 2022). "Most importantly, urinary FBLN1 and exosomal miR-1269b levels were correlated with the severity of kidney injury in type 2 diabetic patients." (PMID 34977033, 2021). "The association between fibulin-1 and PWV in patients with type 2 diabetes remains to be elucidated." (PMID 23866070, 2013). "A second major finding was that plasma fibulin-1 levels were lower in patients with type 2 diabetes compared with controls." (PMID 23866070, 2013). "Further, it was evident that the high arterial stiffness population was significantly different from the control subjects in terms of plasma fibulin-1, baPWV (1,811 ± 367.0 vs. 1,193 ± 119.7 cm/s, p < 0.001), blood pressure, blood lipids, type 2 diabetes, hyperlipidemia, age, and AI." (PMID 35872882, 2022). "In addition, fibulin-1 is related to the amino-terminal prohormone B-type natriuretic peptide (NT-proBNP) in type 2 diabetes and African patients subjected to early vascular ageing." (PMID 25014213, 2014). "Although definite mechanisms on fibulin-1′s role in extracellular matrix remodelling, especially in clinical situations such as type 2 diabetes, atherosclerosis, cardiac ischemia and heart failure, remain to be elucidated, some evidence exists indicating its role in some of these conditions." (PMID 25014213, 2014). "The present findings extend on previous observations by the demonstration of an independent association between plasma fibulin-1 levels and carotid-femoral PWV, the gold standard method for assessment of arterial stiffness, in patients with recently diagnosed type 2 diabetes." (PMID 23866070, 2013). "Interestingly, the elastin-associated ECM molecule fibulin-1 was recently identified in non-atherosclerotic arterial tissue from patients with type 2 diabetes." (PMID 23866070, 2013). "Whether plasma fibulin-1 is associated with arterial stiffness at earlier phases of type 2 diabetes has not been determined." (PMID 23866070, 2013). "It was found in our research that the high arterial stiffness group (baPWV ≥ 1,400 cm/s) had a higher plasma concentration of fibulin-1 than those with normal arterial stiffness (baPWV < 1,400 cm/s) after adjusting for blood pressure, FBG, blood lipid, Type 2 diabetes, and hyperlipidemia." (PMID 35872882, 2022). "Yet, as the plasma level of fibulin-1 was lower in patients with recently diagnosed type 2 diabetes than in healthy controls, plasma fibulin-1 levels are not a simple marker of the degree of arterial stiffening." (PMID 23866070, 2013). "Recently, we applied gene expression microarrays and identified fibulin-1 (FBLN1) as a molecular marker of cardiovascular disease in non-atherosclerotic tissue from patients with type 2 diabetes." (PMID 22340758, 2012).
type 2 diabetes (continued). "Furthermore, Fibulin-1, an important extracellular matrix (ECM) protein involved in matrix organization, has been found to accumulate in the wall of the IMA of patients with type 2 diabetes." (PMID 29684625, 2018).
atherosclerosis (6 papers, 2014 to 2024). A disease characterized by the build-up of fatty material and calcium deposition in the arterial wall resulting in partial or complete occlusion of the arterial lumen. "Differences in FBLN1 abundance have previously been observed in several studies, including its relationship to atherosclerosis, cardiovascular risk, arterial stiffness and type 2 diabetes (T2D)." (PMID 29907817, 2018). "Our study population was clinically diagnosed with asymptomatic aortic stenosis, particularly chosen to evaluate fibulin-1′s role in fibrotic and sclerotic processes in relation to cardiac overload and subclinical atherosclerosis-related inflammation." (PMID 25014213, 2014). "Previous studies have shown that there are significant deposits of fibulin-1 in atherosclerotic lesions and thrombus, and fibulin-1 may thus play a role in the process related to the progression of atherosclerosis and thrombotic complications in humans." (PMID 35872882, 2022). "In addition, people with coronary heart disease, atherosclerosis, hyperuricemia, liver and kidney diseases, hypertension, and medication were eliminated to exclude the influence of diseases on the plasma concentration of fibulin-1 in our study." (PMID 35872882, 2022). "The authors also argued that FBLN1 can influence the transforming growth factor-β (TGF-β) pathway to regulate EMT, which was verified as the vital role in cardiovascular cells and in many cardiovascular diseases, such as hypertension, cardiac hypertrophy, atherosclerosis and restenosis." (PMID 32430056, 2020).
aortic stenosis (5 papers, 2012 to 2025). Aortic valve stenosis is a aortic valve disease caused by the incomplete opening of the aortic valve. "Plasma fibulin-1 levels have been investigated in patients with aortic stenosis, where an association with decreased longitudinal systolic LV function has been observed." (PMID 28068900, 2017). "In conclusion, elevated levels of plasma fibulin-1 were associated with aortic stenosis, elevated LV hemodynamic load as indicated by elevated levels of NT-proBNP and soluble uPAR supporting a possible link in cardiovascular extracellular sclerotic processes." (PMID 25014213, 2014). "Fibulin 1 was found to beassociated with NT-proBNP levels in patients with aortic stenosis, HF, and apopulation composed of African individuals." (PMID 40026492, 2025). "Fibulin-1 is a novel biomarker and high concentrations have primarily been reported in patients with aortic stenosis and DM compared to a level of 5.6 (4.1–8.4) μg/mL reported in healthy men." (PMID 28068900, 2017). "Both fibulin-1 (p = 0.045) and NT-proBNP (p = 0.018) levels were higher in the moderate aortic stenosis group, whereas suPAR levels were similar (p = 0.44)." (PMID 25014213, 2014). "The levels of fibulin-1 and NT-proBNP increased independently parallel to increasing severity of the aortic stenosis." (PMID 25014213, 2014). "This prospective study suggests that fibulin-1 and soluble uPAR are involved in myocardial extracellular matrix turnover as a result of elevated LV overload in patients with aortic stenosis." (PMID 25014213, 2014). "In patients with symptomatic severe aortic stenosis undergoing AVR, plasma fibulin-1 is associated with restrictive filling of the LV, decreased longitudinal systolic function of the LV, and increased LV filling pressures." (PMID 23316326, 2012). "Plasma fibulin-1 levels have been suggested to be an early plasma marker of aortic stenosis." (PMID 35317720, 2022). "The lack of association between fibulin-1 and echocardiography data may be due to unrecognised myocardial fibrosis in the asymptomatic and less severe nature of aortic stenosis of this cohort." (PMID 25014213, 2014). "One hundred twenty-five patients with severe aortic stenosis who were scheduled for aortic valve replacement (AVR) were evaluated with preoperative echocardiography and their plasma fibulin-1 levels were determined with ELISA." (PMID 23316326, 2012). "Change in aortic stenosis progression, bicuspid/tricuspid aortic valve myocardial hypertrophy and LV function were not related to baseline fibulin-1 or changes in fibulin-1 (all p>0.099; data not shown)." (PMID 25014213, 2014).
bladder cancer (5 papers, 2014 to 2023). "We conjectured that the methylation degree of FBLN1 promoter increased in the progression progress of bladder cancer, which resulted in the loss of fibulin-1 expression, so that enhanced the bladder tumor growth and ability of metastasis and angiogenesis." (PMID 25234557, 2014). "These tumor suppressing functions of FBLN1 corresponded with its loss of expression in bladder cancers." (PMID 25234557, 2014). "The promoter region of FBLN1 was generally methylated in bladder cancer cell lines and tissues, further investigation in patient tissues showed that the methylation status was associated with the fibulin-1 expression." (PMID 25234557, 2014). "Our findings from in vitro and in vivo experiments proved that overexpressing fibulin-1 suppressed tumor growth, induced tumor cell apoptosis, decreased cell motility, and inhibited angiogenesis in bladder cancer cells." (PMID 25234557, 2014). "Further studies are needed to determine the potential usefulness of assessing FBLN1 in bladder cancer as a prognostic marker and candidate target for gene therapy." (PMID 25234557, 2014). "Remarkably, we found the transcription level of fibulin-1 in bladder cancer cells increased as expected after 5-AZA-dC treatment, but it was still well below that in bladder non-tumorgenetic cell line SV-HUC-1." (PMID 25234557, 2014). "Using methylation-specific PCR and quantitative sequencing, we found the promoter regions of fibulin-1 were generally methylated in bladder cancer cell lines (5637, HT1376, J82 and T24) and tissues." (PMID 25234557, 2014). "Together, these results suggested that fibulin-1 was down-regulated through promoter hypermethylation in bladder cancer." (PMID 25234557, 2014). "We used real-time PCR, Western blot analysis and immunohistochemistry to determine the expression of fibulin-1 in Bladder cancer cells and patient tissues respectively." (PMID 25234557, 2014). "Eukaryotic expression plasmid and lentiviral vector were used to overexpress fibulin-1 in Bladder cancer cells 5637, HT-1376 to investigate its function in vitro and in vivo." (PMID 25234557, 2014). "Restoration of fibulin-1 expression significantly inhibited bladder cancer cell growth, motility and angiogenesis, which are indicative features of tumor suppressor gene." (PMID 25234557, 2014). "However, the association between fibulin-1 and bladder cancer remains unknown." (PMID 25234557, 2014). "Our data revealed the expression of fibulin-1 was significantly decreased or lost in bladder cancer tissues and cell lines." (PMID 25234557, 2014). "Overexpression of fibulin-1 significantly suppressed tumor growth, induced tumor cell apoptosis, decreased cell motility, and inhibited angiogenesis in cultured bladder cancer cells and xenograft tumor in nude mice." (PMID 25234557, 2014). "Compared to SV-HUC-1 cells, all of bladder cancer cell lines had a significantly lower level of fibulin-1 expression in both mRNA and protein levels." (PMID 25234557, 2014). "Fibulin 1 was epigenetically down regulated in bladder cancer." (PMID 37822814, 2023). "Fibulin-1 down regulation was associated with the non-muscleinvasive bladder cancer grade and recurrence." (PMID 37822814, 2023). "Fibulin 1 act as a tumour suppressor gene and angiogenesis inhibitor in bladder cancer." (PMID 37822814, 2023). "So here we investigated the expression and function of fibulin-1 in Bladder cancer." (PMID 25234557, 2014). "We identified that fibulin-1 was significantly down-regulated in bladder cancer, and its dysregulation was associated with non-muscle-invasive bladder cancer (NMIBC) grade and recurrence." (PMID 25234557, 2014). "In conclusion, our study provides evidences that FBLN-1 functions as a novel candidate tumor-suppressor gene in bladder cancers and its down-regulation maybe due to the promoter hypermethylation." (PMID 25234557, 2014).